HOXB13 (homeobox B13)
Diseases named in the same sentence as HOXB13 in open-access papers (continued):
Sharing a sentence is not in itself a finding about the gene and the disease.
prostate carcinoma (continued). "The results presented that HOXB13 p.Gly84Glu mutation contributed to the susceptibility of prostate cancer (OR = 3.248, 95% CI = 2.313−4.560, P < 0.001)." (PMID 26517352, 2015). "In our data example, we obtained confirmatory evidence of the association of the HOXB13 G84E mutation with prostate cancer, and provided age-specific risks for developing prostate cancer for mutation carriers in a large, prospective cohort." (PMID 25629170, 2015). "A rare HOXB13 polymorphism (G84E) occurring in 0.1–0.6% of European/American populations has been linked to an increased prostate cancer risk by several groups." (PMID 25825985, 2015). "In recent years, HOXB13 p.Gly84Glu mutation was found to contributed to the risk of prostate cancer, especially in European countries." (PMID 26517352, 2015). "Recent data have established HOXB13 as a strong candidate gene for causing hereditary prostate cancer if mutated." (PMID 25825985, 2015). "HOXB13 is a prostate cancer susceptibility gene which shows a cancer predisposing (G84E) mutation in 0.1–0.6% of males." (PMID 25825985, 2015). "For example, a recent study suggested that one cannot adequately impute the HOXB13 G84E mutation associated with prostate cancer risk (carrier frequency of 0.0034 in European ancestry participants in the 1000 Genomes Project)." (PMID 25629170, 2015). "In order to gain insight into the full scope of coding HOXB13 mutations in Portuguese prostate cancer patients, we decided to sequence the entire coding region of the HOXB13 gene in 462 early-onset or familial/hereditary cases." (PMID 26176944, 2015). "Extensive analysis has revealed that mutations in the HOXB13 gene are associated with a significantly increased risk of hereditary prostate cancer." (PMID 25944620, 2015). "The strong association of HOXB13 with positive ERG status expression fits well with the known role of androgen receptor activation for development of ERG fusions in prostate cancer." (PMID 25825985, 2015). "In summary, the meta-analysis suggested that HOXB13 p.Gly84Glu mutation contributed to the overall cancer risk, especially for prostate cancer." (PMID 26517352, 2015). "The only clearly damaging variant was rs138213197, which encodes a change from Glycine to Glutamate in the HOXB13 gene, and was previously reported to be associated with a high risk of prostate cancer." (PMID 24497837, 2014). "Penetrance (age-specific cumulative risk) and 95% confidence intervals of prostate cancer for carriers of the HOXB13 missense mutation G84E (rs138213197) by selected years of birth." (PMID 23457453, 2013). "By sequencing coding regions of more than 200 genes in a previously identified region of linkage at 17q21–22 a rare but recurrent mutation (G84E) in HOXB13 was recently identified in four of 94 probands from prostate cancer families." (PMID 23064873, 2013). "This study has also shown that the majority of hereditary prostate cancers due to the HOXB13 missense mutation are ‘sporadic’ in the sense that unselected cases with the missense mutation do not typically report having a family history of prostate cancer." (PMID 23457453, 2013). "The estimated frequency of the HOXB13 G84E mutation in prostate cancer families is influenced by the number of individuals in any given family as well as family structure." (PMID 23064873, 2013). "We repeated our analyses excluding families from the University of Michigan and Johns Hopkins Hospital, some of which were included in the initial report describing HOXB13 as a prostate cancer susceptibility gene." (PMID 23064873, 2013). "Our study has provided a population-based estimate of the average risk of prostate cancer for HOXB13 missense mutation G84E carriers that can be used to guide clinical practice and research." (PMID 23457453, 2013). "The HOXB13 missense mutation G84E (rs138213197) has been reported to be associated with increased risk of prostate cancer." (PMID 23457453, 2013).
prostate carcinoma (continued). "Of the 23 newly identified susceptibility loci for prostate cancer, rs11650494 is located at chromosome 17q21, a gene-dense locus that contains several prostate cancer candidate genes such as HOXB13 and SPOP." (PMID 23852643, 2013). "Recently, a rare, recurrent mutation (G84E) in HOXB13 was reported to be associated with prostate cancer risk." (PMID 23064873, 2013). "In summary, analysis of the large ICPCG family collection establishes the HOXB13 G84E allele as a reproducible risk factor for prostate cancer." (PMID 23064873, 2013). "An analogous case in prostate cancer is the altered target gene spectrum of the androgen receptor caused by changes in the expression of interacting transcription factors like HOXB13 and FOXA1." (PMID 24213107, 2011). "Furthermore, a HOXB13 germline variant has been associated with increased risk for developing prostate cancer." (PMID 40137996, 2025). "This study examines the mutations in BRCA2 and HOXB13 which are some of the best described genes associated with hereditary prostate cancer, emphasizing the rationale of why RFLP could aid in the early diagnosis of patients in regions lacking NGS capabilities." (PMID 40433050, 2025). "Likewise, our results suggest HOXB13 mutations are independently associated with prostate cancer risk." (PMID 40433050, 2025). "Meanwhile, genetic studies have implicated HOXB13 variants and the 8q24 locus in prostate cancer progression, which may partially explain observed racial differences." (PMID 41413487, 2025). "HOXB13 (G84E) Variant: This variant shows the most substantial increase in risk, with carriers having a 20-fold increased likelihood of developing hereditary prostate cancer." (PMID 41541272, 2025). "HOXB13 was the first gene conclusively linked to familial prostate cancer." (PMID 41440226, 2025). "Patients with symptomatic Benign Prostatic Hyperplasia (BPH) showed upregulated gene expression of biological pathways associated with T cell activation and suppression of a key transcription factor HOXB13, which is associated with transcription and epigenetic regulation of prostate cancer (PCa)." (PMID 38201640, 2024). "The only prior study of epigenetic regulation of FASN has suggested that HOXB13 may function to repress FASN expression in prostate cancer cells, while the HOXB13 G84E mutation may lead to FASN derepression and increased expression." (PMID 38112617, 2024). "HOXB13 encodes a transcription factor which contributes to germline risk of prostate cancer." (PMID 36882784, 2023). "HOXB13 mutations are also associated with an increased hereditary prostate cancer risk." (PMID 36937425, 2023). "The exception is HOXB13 which, to date has only been associated with prostate cancer." (PMID 35732815, 2022). "Variants in DDR genes and HOXB13 may be important cancer risk factors for Black men diagnosed with early-onset prostate cancer, and are more frequently observed in men with a family history of cancer." (PMID 36446039, 2022). "For example, a targeted sequencing study of a cohort of 5,083 prostate cancer patients has shown that 1.4% of prostate cancer patients have a recurrent G84E mutation in HOXB13, which increases in prevalence to 3.1% among early-onset prostate cancer patients with family history of the disease." (PMID 36212399, 2022). "The HOXB13 G84E allele accounts for approximately 5% of hereditary prostate cancer." (PMID 35785170, 2022). "Reports have linked the HOXB13 germline variant (G84E, rs138213197) to an increased risk of prostate cancer in men of European descent and also found an increase in overall cancer risk in a pooled analysis of 25 epidemiological studies with 145,257 participates." (PMID 36315513, 2022). "In Poland, mutations in HOXB13 are the cause of 0.6% unselected cases of prostate cancer." (PMID 34983599, 2022). "Our study observed that the prostate cancer risk that this locus carries can significantly exceed that which may be appreciated by testing HOXB13 G84E alone." (PMID 34059701, 2021).
prostate carcinoma (continued). "HOXB13 gene mutations are often detected in prostate cancer patients." (PMID 34917121, 2021). "Epidemiologic studies of prostate cancer could analogously be impacted by an incomplete ability of HOXB13 G84E to fully capture locus risk." (PMID 34059701, 2021). "Other gene variants were also analyzed using such programs such as V66 M variant of human BDNF in psychiatric disorders and computational modeling of complete HOXB13 protein for predicting the functional effect of SNPs and the associated role in hereditary prostate cancer." (PMID 32115674, 2020). "HOXB13 is also expressed in some adult tissues and known as an oncogenic transcription factor that is associated with the malignancy of ovarian cancer, prostate cancer, and also lung adenocarcinoma; however, the physiological/pathophysiological role of HOXB13 remains controversial." (PMID 32998228, 2020). "Interestingly, HOXB13 is preferentially recruited to the risk allele of a prostate cancer risk associated SNP, rs339331, located in an enhancer element upstream of RFX6, thereby enhancing RFX6 expression and promoting more aggressive disease." (PMID 32546843, 2020). "Germline mutations in DNA damage repair genes and the transcription factor HOXB13 are associated with prostate cancer and may be targeted therapeutically." (PMID 32197306, 2020). "Since HOXB13 p.G84E is a prostate cancer risk allele, we evaluated the association between HOXB13 germline mutations and breast cancer risk in a previous study consisting of 3,270 familial non-BRCA1/2 breast cancer cases and 2,327 controls from the Netherlands." (PMID 32546843, 2020). "It remains to be demonstrated whether regular screening for HOXB13 G84E mutations in men with strong family history of prostate cancer can result in improved outcomes." (PMID 32197306, 2020). "Men with a G84E mutation in the HOXB13 gene are at a high risk of developing prostate cancer." (PMID 30527799, 2019). "Specifically, several missense rare mutations in HOXB13, including G84E, Y88D, L144P, G216C, and R229G, have been identified in association with increased prostate cancer susceptibility through targeted germline DNA sequencing of the 17q21-22 region in a cohort of 94 prostate cancer patients." (PMID 31013831, 2019). "Thus far several genes have been associated with prostate cancer risk including HOXB13, NBS1 and CHEK2." (PMID 30036379, 2018). "The HOXB13 G84E variant is associated with risk of prostate cancer (PCa), however the role this variant plays in PCa development is unknown." (PMID 29259341, 2017). "The results indicate that HOXB13 G84E is a heritable variation associated with prostate cancer." (PMID 28598379, 2017). "Moreover, fine-scale mapping at the HOXB gene cluster at 17q21–22 had identified a number of highly correlated common SNPs that were associated with prostate cancer risk and tagging the rare HOXB13 p.G84E variant." (PMID 27424772, 2016). "Moreover, HOXB13 was shown to preferentially bind a low-risk prostate cancer susceptibility allele located in an AR and FOXA1 binding site (i.e. rs339331), thereby enhancing RFX6 expression and promoting metastasis." (PMID 27424772, 2016). "Furthermore, HOXB13 expression was associated with a more aggressive prostate cancer phenotype and was considered an independent predictor of unfavorable outcome." (PMID 28050579, 2016). "Recently, HOXB13 was identified as a site-specific susceptibility gene for prostate cancer when Ewing and his colleagues found a recurrent germline mutation (G84E, rs138213197) in men of European descent, which co-segregated with the disease in affected families." (PMID 28050579, 2016). "The HOXB13 p.G84E mutation has been firmly established as a prostate cancer susceptibility allele." (PMID 27424772, 2016). "The rs138213197 C>T in HOXB13, yielding a rare G84E missense variant, significantly increases the risk of prostate cancer, and the biological function of this 84E remains unclear." (PMID 26967244, 2016).
prostate carcinoma (continued). "Given the potential importance of HOXB13 for prostate cancer development, we wondered whether HOXB13 expression levels would be linked to disease outcome or relevant clinical or molecular subgroups." (PMID 25825985, 2015). "Furthermore, we evaluated the prevalence of somatic HOXB13 mutations in PrCa by sequencing the HOXB13 coding region of 178 prostate carcinomas." (PMID 26176944, 2015). "Additionally, we searched for somatic HOXB13 mutations in 178 prostate carcinomas to evaluate their prevalence in prostate carcinogenesis." (PMID 26176944, 2015). "The HOXB13 gene has been implicated in prostate cancer (PrCa) susceptibility." (PMID 24550738, 2014). "Interestingly, by exome sequencing 202 genes on chromosome 17q21–22, a rare but recurrent germline mutation in the HOXB13 gene (HOXB13 G84E) was reported to be highly associated with familial prostate cancer in Caucasians." (PMID 23852643, 2013). "To examine this finding in a large international sample of prostate cancer families, we genotyped this mutation and 14 other SNPs in or flanking HOXB13 in 2,443 prostate cancer families recruited by the International Consortium for Prostate Cancer Genetics (ICPCG)." (PMID 23064873, 2013). "In this respect, the establishment of a rare and moderate- to high-penetrance mutation in HOXB13 as a prostate cancer susceptibility allele provides empirical evidence for this alternative hypothesis." (PMID 23064873, 2013). "This is also consistent with previous report that HOXB13 acts as repressor of androgen receptor signaling in prostate cancer, which may affect BRCA1 (cofactor associated with AR)." (PMID 23630576, 2013). "In addition, men with BRACA2 or HOXB13 gene variants may have a higher risk of developing life-threatening forms of prostate cancer." (PMID 40558499, 2025). "Transcription factor homeobox B13 (HOXB13) was identified as an upstream regulator of HOXA11-AS.HOXA11-AS regulated bone metastasis-associated C-C motif chemokine ligand 2 (CCL2)/C-C chemokine receptor type 2 (CCR2) signaling in both PC3 prostate cancer cells and SaOS2 osteoblastic cells." (PMID 33514011, 2021). "However, HOXB13 is associated with various renal carcinoma targets involved in the Wnt pathway but combined with the introduction of HOXB13 through the Wnt signal pathway and the androgen receptor signal pathway to inhibit the growth of prostate cancer cells." (PMID 34306077, 2021). "In a recent work, we screened the HOXB13 gene for germline mutations in 462 Portuguese patients with early-onset and/or familial/hereditary prostate cancer and found two novel mutations, A128D and F240L, which seem to confer an increased risk for prostate cancer development." (PMID 28050579, 2016). "While a few genes such as BRCA2 and HOXB13 are definitively linked to prostate cancer risk in specific patient populations, a greater proportion of prostate cancer risk may be associated with common alleles of low-to-intermediate penetrance or private alleles in families contributing to cancer risk." (PMID 26485759, 2015). "In addition, germline mutations of HOXB13 significantly increase risk of hereditary prostate cancer through unknown mechanisms." (PMID 25177484, 2014). "The HOXB13 missense mutation G84E (rs138213197) is associated with increased risk of prostate cancer, but the current estimate of increased risk has a wide confidence interval (width of 95% confidence interval (CI) >200-fold) so the point estimate of 20-fold increased risk could be misleading." (PMID 23457453, 2013). "Various other studies have linked transcriptional regulation of HOXB13 to differential CpG site methylation in the HOXB13 promoter region or gene body in different types of cancers, including prostate cancer, gastric carcinomas, and breast cancer." (PMID 40137996, 2025).
prostate carcinoma (continued). "In the present study, we searched for protein partners of HOXB13 by immunoaffinity purification followed by high-throughput mass spectrometric analysis (IP/LC-MS) using the PC-3 prostate cancer cell line as a model." (PMID 41164275, 2025). "The greatest prostate cancer risk is associated with variations in two DNA damage repair genes, BRACA2 and HOXB13." (PMID 40558499, 2025). "The genotyping data showed 39 subjects with mutations of prostate cancer cases from PCR- RFLP analysis, including 26 positives for BRCA2 and 13 positives for HOXB13 mutations." (PMID 40433050, 2025). "Previous studies using the VCaP prostate cancer cell linehave shown that HOXB13 precipitates with the EED protein,which is a component of the PRC2 repressor complex (Cao etal., 2014)." (PMID 41164275, 2025). "YTHDC1 can form a complex with SLC12A5 to upregulate HOXB13, leading to the promotion of prostate cancer progression." (PMID 40221424, 2025). "Recent evidence suggests that HOXB13 plays critical AR-independent functions in repressing lipogenic programs and promoting prostate cancer (PCa) metastasis." (PMID 41277556, 2025). "Using the DepMap resource, we have shown that one of the identified partners, the TBX3 protein is as critical for the growth and proliferation of prostate cancer cell lines in vitro as HOXB13." (PMID 41164275, 2025). "Genotyping of the HOXB13 and BRCA2 genes in both prostate cancer cases and controls identified significant associations between specific alleles of these genes and prostate cancer." (PMID 40433050, 2025). "Analysis of individual prostate cancer cell lines revealed that knockout of both genes, HOXB13 and TBX3, leads to the death of the same lines: VCaP, LNCaP (clone FGC), PC-3 and 22Rv1." (PMID 41164275, 2025). "In the present study we used IP/LC-MS to identify the proteinpartners of HOXB13 in the PC-3 prostate cancer cell line." (PMID 41164275, 2025). "In prostate cancer cells, one of the key transcriptional regulators is the HOXB13 (Homeobox B13) protein." (PMID 41164275, 2025). "Both HOXB13K13A mutants and parental cells displayed similar levels of sensitivity to the CBP/p300 inhibitor A-485 or GNE-049, suggesting that in prostate cancer, HOXB13 lysine 13 acetylation confers a therapeutic vulnerability to DNA-damaging therapies." (PMID 38730575, 2024). "For instance, the acetylated homeobox B13 (HOXB13) plays a role in controlling ACK1 gene transcription in prostate cancer by establishing a CRPC-specific SE, thereby affecting tumor growth." (PMID 38410974, 2024). "Together, our results reveal an important role for HOXB13 in the maintenance of genome integrity of prostate cancers." (PMID 38730575, 2024). "We demonstrate a novel mechanism by which HOXB13 promotes radio- and chemoresistance of prostate cancers." (PMID 38730575, 2024). "Conversely, targeting HOXB13-regulated transcriptional networks with bromodomain kinase inhibitors has shown therapeutic efficacy in castration-resistant prostate cancer models." (PMID 38201640, 2024). "Prostate cancer cells rely on AR, HOXB13 and FOXA1-regulated transcriptional programs for tumor progression and resistance to anti-androgens." (PMID 38730575, 2024). "In contrary, overexpression of HOXB13 in prostate cancer cells led to an increase in PSMA expression levels." (PMID 37569712, 2023). "Along this line, one of the best case studies for prostate cancer is HOXB13, which has been described in several instances to be both overexpressed and required for prostate cancer cell proliferation and metastasis." (PMID 36611993, 2023). "Genes that are of high importance in our RF models that are associated with both LCC and prostate cancer include PRAC1, HOXB13, SPAG16." (PMID 37434131, 2023). "Homeobox B13 (HOXB13), a transcription factor of prostate cancer cells, regulated the long noncoding RNA HOXA11-AS to promote the transcription level of integrin αVβ1 and aggravate bone metastasis." (PMID 37037822, 2023).